ZEB2 (zinc finger E-box binding homeobox 2)
Diseases named in the same sentence as ZEB2 in open-access papers (continued):
Sharing a sentence is not in itself a finding about the gene and the disease.
tumor (continued). "Phenotypes underlying such clustering patterns showed that CTCs maintained higher expression than all tumor cell lines for FOXC1, KRT18, PTEN, NPTN, TGFß1, KRT8, ZEB2, and CXCR4." (PMID 22586443, 2012). "Further analysis showed that overexpression of cytoplasmic ZEB2 in HCCs was inversely correlated with AFP level, tumor size and differentiation (P<0.05)." (PMID 22393452, 2012). "miR-200a and its orthologs, miR-200b, miR-200c, and miR-141 were first found tumor suppressors as they inhibit EMT through targeting Zeb1 and Zeb2." (PMID 23144891, 2012). "The miR-200 family is largely known as tumor suppressive because of its inhibition of the epithelial-mesenchymal transition (EMT) through direct targeting of Zeb1 and Zeb2 TFs." (PMID 23144891, 2012). "ZFP36L1 targets mRNAs involved in tumor progression, such as FGF21, ZEB2, and Cyclin D." (PMID 41285712, 2025). "Nevertheless, in the seven-gene model, the remaining four genes—PLK1, TRAF2, SLCO1B3, and ZEB2—though not consistently expressed in tumor epithelial cells, also exhibit either oncogenic or tumor-suppressive functions." (PMID 41187171, 2025). "Ectopic expression of ZEB1 significantly reduced the ferroptosis defense of 2D but not 3D CRCs, while silencing ZEB1 or ZEB2 promoted the antiferroptosis ability of both 2D and 3D tumor cells." (PMID 39985376, 2025). "To further evaluate whether ZEB2 knockout had any direct impact on the intrinsic properties of the tumor cells, such as cell viability, we performed CCK-8 assays on ZEB2 knockdown PC9-GR and HCC827-GR cells." (PMID 40510028, 2025). "SNAI1 also known as ZEB2 (zinc finger E-box binding homeobox 2), as well as ZEB1, E2-2 (as also known as transcription factor 4) and Twist, were all up-regulated in ECSs, similar to other tumor types." (PMID 38836981, 2024). "The animals were sacrificed, and the tumor tissue from stressed animals exhibited increased mRNA expression of the EMT-related genes Twist1, Twist2, Zeb1, Zeb2, Slug, and PLAGL2 and increased protein expression of PLAGL2, Ki67 (a proliferation marker), N-cadherin, and Vimentin." (PMID 38689092, 2024). "The high correlation of ETS1 with ZEB2 in the TCGA BRCA RNA-seq data may confirm its oncogene role, but this is most likely a consequence of their correlations with tumor purity." (PMID 36109686, 2023). "Recent studies revealed a direct negative feedback loop between miR-203a and ZEB2 participating in tumor stemness and chemotherapy resistance, in which increased miR-203a expression sensitized cancer cells to cisplatin in vitro." (PMID 35453574, 2022). "According to our scRNA-seq data, the ZEB2 expression did not significantly correlate with the p-EMT program in the level of individual tumor cell." (PMID 36127333, 2022). "In line with RT-PCR results, we found that ZEB2 was highly expressed in L6 tumor cells, while L5 was completely negative and L7 showed only few positive tumor cells." (PMID 35837106, 2022). "In addition, our in vitro experiments also demonstrated that the ZEB2 expression of UM-Chor1 was significantly downregulated after the application of inhibitors, which targeted TGFBI, and the invasiveness of tumor cells was correspondingly attenuated." (PMID 36127333, 2022). "Activation of MEK1/2 and ERK1/2 promotes tumour progression by ZEB1 and ZEB2." (PMID 36499447, 2022). "Inversely, high levels of ZEB2 may impact on negative regulation on subsets of shared SMAD/ZEB2 target genes in or around tumors where upstream ligands such as TGFβ and/or BMP co-create the tumor contexts." (PMID 34356053, 2021). "A 15.9‐month reduction in mean OS (log‐rank, P < 0.002) and 19.5‐month reduction in mean DFS (log‐rank, P < 0.002) were observed in patients with ZEB2‐positive tumours when compared to ZEB2‐negative ones." (PMID 33931939, 2021).
tumor (continued). "Furthermore, this panel revealed the potential colocalization of multiple tumor cell markers such as β-catenin, ADAM10, ZFX, and ZEB2." (PMID 34490110, 2021). "Another tumour suppressor transcript that is downregulated in COM is miRNA-205, which exerts growth inhibitory and anti-migration effects by repressing EGFR superfamily member ERBB3 and zinc-finger E-box binding homeobox 2 (ZEB2), respectively." (PMID 34822659, 2021). "ZEB2 overexpression upregulated pCRAF/pASK1 levels resulting in increased chemoresistance, enrichment of cells with stemness/EMT traits and proliferative slowdown of tumor xenografts." (PMID 31910865, 2020). "The tumor suppressor miR200c inhibits the epithelial–mesenchymal transition, a process involved in metastasis by enhancing the motility and migration of tumor cells, by targeting ZEB1 and ZEB2." (PMID 32498278, 2020). "In certain tumor cells, SNAI1 upregulates ZEB1 and ZEB2 expression." (PMID 32226439, 2020). "Western blotting showed that compared with the EMT model group, FH could significantly increase E‐cadherin and reduce Snail2, ZEB2, TWIST1, and TGFβ1 protein expression in TNBC xenograft tumor zebrafish (P < .01.05)." (PMID 32037729, 2020). "Zeb2 belongs to the ZEB family transcription factors involved in post-implantation (mouse) embryogenesis, organogenesis, and adult cell maturation from progenitors in a number of systems, and tumor progression." (PMID 32260521, 2020). "This suggests the presence of a partial ZEB2-orchestrated EMT program in COSCC, similarly to the SNAI2-driven partial EMT in HNSCC, which is clearly distinct from full EMT programs or “mesenchymal” tumor signatures derived from bulk tumor sequencing." (PMID 33142242, 2020). "Interestingly, in a subset of the tumor cells, Twist1 was required for the expression of other EMT-inducing TFs (Snail, Slug, Zeb2), which collaborated with Twist1 to induce pEMT, basal-like tumor progression, and metastasis." (PMID 33297508, 2020). "In addition to a high percentage of VIM-positive tumour cells, MSCCs had a low percentage of CDH1-positive cells and a high percentage of TWIST1-, ZEB1- and ZEB2-positive cells, characteristic of EMT." (PMID 31080552, 2019). "The direct correlation between ZEB2 and NR2F1 transcripts is recurrently detected in the luminal tumor samples from all the microarray datasets interrogated in this study whereas it shows a less consistent pattern in the case of samples from basal subtype tumors (brown bars)." (PMID 30087437, 2019). "The novel putative intestinal and pancreatic stem cell marker DCAMKL-1, a microtubule-associated kinase, plays a key role in tumorigenesis by downregulating tumor suppressor microRNAs thus inducing tumor promoters specific targets such as ZEB1, ZEB2, and Notch-1." (PMID 31861725, 2019). "This higher tumor development may be related to higher levels of the EMT transcription factors Snail 2, Zeb1, and Zeb2." (PMID 29949929, 2018). "Our previous reports and this study show that ZEB2 functions as a transcriptional activator by interacting with Sp1 to induce Sp1-regulated genes and thereby contributes not only to EMT/invasion but also to CTC survival and tumor angiogenesis." (PMID 29416649, 2018). "In fact western blot analysis of proteins extracted from A375M/SCD5 tumor nodules, in addition to Snail Family Transcriptional Repressor 1 (SNAI1/SNAIL) and Twist Family BHLH Transcription Factor (TWIST) reduction and ZEB2 up-regulation, showed the induction of E-cadherin." (PMID 29484133, 2018).
tumor (continued). "In considering both tumor and normal samples, miR-34a was inversely correlated with NOTCH1 (r = −0.563, P = 0.001), SLUG (r = −0.374, P = 0.009), ZEB1 (r = −0.505, P = 0.001), and ZEB2 (r = −0.317, P = 0.028) expressions." (PMID 28423483, 2017). "For the mechanism, we found Med19 could regulate the expression of multiple genes relevant to tumor growth and metastasis, including P27, pAKT, pPI3K, IGF1R, E-Cadherin, N-Cadherin, Vimentin, ZEB2, Snail-1 and Snail-2." (PMID 28125713, 2017). "Our findings support a model in which the induction of the EMT regulator ZEB2 by hypoxia and HIF-1α allows tumour cells to flexibly respond to microenvironmental cues and repress repulsive signals such as ephrinB2, enabling cells to diffusely invade the surrounding parenchyma." (PMID 27470974, 2016). "Finally, Expression of miR-203 was negatively correlated with ZEB2 in NPC tissues and cultured tumor spheres." (PMID 27589832, 2016). "While ZEB2 inactivation did not affect tumour vascularization, bevacizumab treatment of G55 tumours significantly reduced vessel density (by 37%) and blocked tumour growth by 95%." (PMID 27470974, 2016). "Finally, we found that miR-203 was negatively correlated with ZEB2 expression in NPC tissues and tumor spheres." (PMID 27589832, 2016). "Interestingly, ZEB2 is an EMT and tumor stemness co-inducer and thus has been confirmed as a direct target of miR-203 in NPC cells." (PMID 27589832, 2016). "Our data demonstrate a directly negative feedback loop between miR-203 and ZEB2 participating in tumor stemness and chemotherapy resistance, highlighting the therapeutic potential of targeting this signal for NPC chemotherapy." (PMID 27589832, 2016). "Taking into the account the co-expression of TWIST1 and ZEB2, we found that patients with expression of both proteins had significantly poorer survival compared to those whose tumor only expressed one or none of the 2 proteins." (PMID 26214683, 2015). "Furthermore, the bevacizumab-treated tumor contained significantly more tumor cells that stained for the EMT markers matrix metalloproteinase 2 (MMP2), Zinc-finger E box-binding homeobox 1 (Zeb1), Zeb2, Snail, Slug and Twist." (PMID 25957416, 2015). "Here we could see a clear IL-7-dependent survival effect of the derived Zeb2-overexpressing mouse T-ALL cell lines in vitro and an effect on their ability to initiate secondary tumours after transplantation." (PMID 25565005, 2015). "Presumably, tumor cells in patients with low NKX2.2 levels and/or high ZEB2 levels are further along mesenchymal differentiation and may exhibit pronounced migratory characteristics, allowing them to metastasize to distal sites with enhanced capacity." (PMID 26000096, 2015). "Consistent with the observed down-regulation of RFX2, ZEB2, and CRIM1 regions using qRT-PCR, in-situ hybridizations with probes corresponding to these genomic loci clearly reveal that these loci are down-regulated in tumor epithelium." (PMID 25798919, 2015). "Our data suggest that ZEB2 expression in RCC may facilitate an increased malignant feature and/or a worse prognosis in this tumor type." (PMID 23658743, 2013). "However, other in vitro studies of TGF-β-induced EMT have identified miR-155, by RhoA targeting, and especially the miR-200 family in tumor metastasis, by targeting E-cadherin transcriptional repressors ZEB1/ZEB2, as EMT-promoting miRNAs." (PMID 23441172, 2013). "Additionally, ZEB2 upregulation of the EMT and tumor invasion-related genes, such as E-cadherin, vimentin, and metalloproteases, have been reported." (PMID 23658743, 2013). "Also, ZEB2-mediated upregulation of EMT and tumor invasion related genes, such as E-cadherin, vimentin and metalloproteases, have been indicated." (PMID 22393452, 2012).
tumor (continued). "The most well-known function of the miR-200 family and miR-205 is their ability to regulate the expression of E-cadherin transcriptional repressors ZEB1 (also known as δEF1) and SIP1 (also known as ZEB2), factors important for epithelial mesenchymal transition (EMT) and tumor metastasis." (PMID 22514717, 2012). "Accordingly, over-expression of ZEB2 and TWIST1 in surgical samples of both normal and tumor tissues can induce EMT, resulting in over-expression of representative EMT markers VIM, FN, and COLs and membrane signal transducers IL8, CXCL4, CCL5, CXCR4, PDGFRB, and TLR2." (PMID 21533028, 2011). "Consequently, ZEB2 expression may serve as a prognostic biomarker in LSC, alongside E-cadherin, which acts as an EMT biomarker reflecting oncogenesis, tumor development, and metastasis of LSC." (PMID 40231252, 2025). "In addition to a number of reported mRNA transcripts, such as ILEI, EGFR, MOESIN, FAM3C, JAK2 and EIF5A2, we identified ZEB2, an EMT‐related transcription factor that is vital for tumor metastasis, as a potential transcript regulated by PCBP1 at the translational level." (PMID 41117067, 2025). "miR-653 plays as a tumour suppressor in CRC progression, and serum exosomal hsa-circ-0004771 may be a predictive biomarker for 5-FU-resistance in CRC patients, potentially through miR-653/ZEB2 axis." (PMID 37845688, 2023). "Thus, future studies may be directed towards understanding the relationship between ZEB2 and ARHGAP31 proteins and their functions in the process of initiating treatment of tumours by performing functional analysis." (PMID 37927751, 2023). "Besides, in Li MZ’ report in 2017, ZEB2 was also overexpressed in clinical CRC tissues samples, and played an oncogenic role, promoting cell proliferation, metastasis, epithelial-mesenchymal transition, tumor growth, and tumor formation." (PMID 37845688, 2023). "Studies have shown that FOXA2 could function as a tumor suppressor by selectively binding to the promoter of several genes related to epithelial–mesenchymal transition (EMT), such as Slug, CDH1 or Zeb2, to suppress tumor migration and progression in lung cancer, breast cancer or liver cancer." (PMID 38072043, 2023). "Emerging evidence suggests that ZEB2 plays a crucial role in EMT-induced processes, including development, differentiation, and malignant mechanisms, such as drug resistance, cancer stem cell-like characteristics, apoptosis, survival, cell cycle arrest, tumor recurrence, and metastasis." (PMID 35723302, 2022). "Combined with the expression of ZEB2 in COAD, this indicates that the patient’s immune system may be significantly suppressed in COAD, allowing the development of a microenvironment that promotes tumorigenesis and tumor development." (PMID 36072677, 2022). "In addition, miR-342-3p overexpression-mediated anti-tumor effects in NSCLC cells were largely reversed by the accumulation of ZEB2, suggesting that miR-342-3p restrained NSCLC progression largely by downregulating ZEB2 expression in vitro." (PMID 34839824, 2021). "In GBM, miR-139-5p may suppress tumor cell invasion and migration via targeting ZEB1 and ZEB2." (PMID 34001135, 2021). "No ZEB2‐negative primary tumour exhibited ZEB2 in the recurrence." (PMID 33931939, 2021). "Thus, the activation of the ZEB2/pCRAF/pASK1 axis induced the increase prevalence of quiescent cancer stem cells (QCSCs), with a stemness/EMT phenotype followed by the chemotherapy treatment of tumour xenografts, especially in a chemotherapy-quiescent state." (PMID 32503256, 2020).
tumor (continued). "Thus, tumor budding cells have been shown to have reduced expression of miR‐200b and miR‐200c, while on the other hand they exhibit increased expression of ZEB1 and ZEB2." (PMID 31295960, 2019). "Therefore, we hypothesized that, by cooperating with Sp1, ZEB2 drives diverse cellular functions other than EMT and tumor invasiveness during tumor progression." (PMID 29416649, 2018). "Additionally, expression levels of the downstream markers ZEB-2 and RAB-14 were downregulated, while those of the tumor suppressors CDKN2A, P63, and SIRT-1 were upregulated in the non-tumor specimens of LC patients with underlying respiratory disease compared to non-COPD patients." (PMID 29371906, 2018). "Strikingly, overexpression of ZEB2 in ES cells, which is an EMT-inducing transcription factors (EMT-TF), could repress epithelial phenotypes and facilitate tumor metastasis, which suggests that the transition of cellular plasticity might participate in the tumor metastasis of ES." (PMID 28055964, 2017). "However, evaluation of a number of genes (Zeb1, Zeb2, Twist, vimentin, etc) associated with EMT did not support the idea that SPC-IGFIR-Akt2−/− tumor cells had undergone EMT." (PMID 26654940, 2016). "Finally, we performed immunohistochemistry on L5, L6 and L7 tumor sections to analyze the expression of ZEB2 (for which we could not find an efficient antibody batch for immunoblotting), E-Cadherin and Vimentin respectively in tumor and stromal cells." (PMID 35837106, 2022). "Thus, in summary, in this study we have shown that miR-449a could be considered as a tumor suppressive miRNA in ER + tumors, and that miR-200c, which targets ZEB1 and ZEB2 (major regulators of EMT) can reverse EMT in our cell line pII an ER-acquired resistance cell line." (PMID 35879960, 2022). "However, there have not been reports demonstrating ZEB2's role in inducing tumor stemness." (PMID 27589832, 2016). "In addition, cytoplasmic overexpression of ZEB2 in HCC tissues was found to correlate with low serum AFP level, small tumor size and well tumor differentiation, and negative correlation of overexpression of cytoplasmic ZEB2 in PLTs and serum AFP level was also observed." (PMID 22393452, 2012). "Both canonical and non-canonical isomiRs targeted well-known drivers of tumor progression, including master regulators of epithelial-mesenchymal transition (EMT), such as ZEB1 and ZEB2 (see ‘Discussion’ for details)." (PMID 36275459, 2022). "WNT4 had decreased expression (logFC = −1.6), and the expression of seven mRNAs (CDK4, MAPK1, TGFB, ZEB2, AURKA, SOX4, and ADAM9) in tumor samples was not notably different from that in the group of normal tissues." (PMID 35453574, 2022). "Although some studies have shown ZEB2 can regulate tumor EMT, and a high ZEB2/E-cadherin ratio predicted poor overall survival 33,34; there are also some studies have shown expression of ZEB2 has nothing to do with EMT nor clinicopathological outcomes." (PMID 33854637, 2021). "By contrast, the inverse correlation observed between the ZEB2 and CDH1 mRNAs is maintained in all the datasets surveyed regardless of the tumor subtype involved (blue bars)." (PMID 30087437, 2019). "Other upregulated genes such as PTEN, ZEB2, STAT3 and IL1B did not align with tumour expression pattern as they are consistently downregulated in the patients datasets." (PMID 30176945, 2018). "Taken together, our studies suggest a negative feedback loop between ZEB2 and miR-203 which promotes NPC pathogenesis by inducing tumor stemness and chemotherapy resistance." (PMID 27589832, 2016). "In MIBC tumor samples, we observed reduced levels for both ZEB1 and ZEB2, and a negative correlation between the expression of the miR-200 family and both ZEB genes." (PMID 26517683, 2015). "The coordinated upregulation or, not uncommonly, overexpression of ZEB1, ZEB2, SNAI1, and VIM and the downregulation of CDH1 indicated that EMT was under way, making the tumor cells assume a mesenchymal phenotype." (PMID 25157365, 2014).